HTR3E (5-hydroxytryptamine receptor 3E)
Description:
Forms serotonin (5-hydroxytryptamine/5-HT3)-activated cation-selective channel complexes, which when activated cause fast, depolarizing responses in neurons.
Synonyms: 5-HT3-E; 5-HT3E; 5-HT3c1
Tractability: Small molecule: an approved drug acts on it; a high-quality ligand is known; it belongs to a druggable protein family. Antibody: UniProt places it where antibodies can reach, with high confidence; its Gene Ontology location is reachable by antibodies, with high confidence; UniProt predicts a signal peptide or a membrane-spanning region. PROTAC: a small molecule that binds it is known.
Gene: Protein-coding gene on chromosome 3 (184,097,064 to 184,106,995, forward strand). Ensembl gene ENSG00000186038.
Subcellular location: Postsynaptic cell membrane; Cell membrane
Pathways (Reactome):
Neuronal System: Neurotransmitter receptors and postsynaptic signal transmission
Gene Ontology:
Molecular function: serotonin-gated monoatomic cation channel activity; extracellular ligand-gated monoatomic ion channel activity; monoatomic ion channel activity; transmembrane signaling receptor activity
Biological process: serotonin receptor signaling pathway; serotonin-gated cation-selective signaling pathway; transmembrane transport; calcium ion transport; monoatomic ion transmembrane transport; monoatomic ion transport
Cellular component: plasma membrane; serotonin-activated cation-selective channel complex; neuron projection; synapse; transmembrane transporter complex; membrane; postsynaptic membrane
Genetic constraint (gnomAD): Loss-of-function variants: 31 observed, 37.16 expected, observed/expected ratio (o/e) 0.83, 90% interval 0.63 to 1.13. The upper end of that interval is the gene's LOEUF score, 1.13, which puts it in group 4 of 6, group 1 being the genes least tolerant of losing a copy. Missense variants: 535 observed, 594.69 expected, observed/expected ratio (o/e) 0.9, 90% interval 0.84 to 0.97. Synonymous variants: 206 observed, 239.12 expected, observed/expected ratio (o/e) 0.86, 90% interval 0.77 to 0.97.
Homologues: Orthologues: chimpanzee HTR3E (91% identical), dog HTR3E (79% identical), macaque HTR3E (79% identical). Paralogues in human: HTR3C (73% identical), HTR3D (54% identical), HTR3A (34% identical), HTR3B (27% identical), CHRNA6 (22% identical), CHRNB2 (21% identical), CHRNA3 (21% identical), CHRNA4 (21% identical), CHRNB4 (21% identical), CHRNA10 (21% identical), CHRNA7 (21% identical), CHRNB3 (21% identical), and 33 more.
Diseases named in the same sentence as HTR3E in open-access papers:
HTR3E is named in the same sentence as 5 diseases in open-access papers, as found by Europe PMC text mining. Sharing a sentence is not in itself a finding about the gene and the disease. The quoted sentences say what the papers report.
depression (1 paper, 2023). "Genes associated with depression or neuro-diseases were found in this study, such as ABCG1, ASMTL, CACNA1F, COX7A1, GRID2, HTR3E, and SHANK2." (PMID 37766304, 2023).
lung carcinoma (1 paper, 2021). "In this study, HTR3 family members were assessed in NSCLC patients, which showed that HTR3C, HTR3D, and HTR3E were amplified with high frequency among lung cancer patients." (PMID 34868311, 2021).
HTR3E also shares sentences with these, for which no sentence is quoted: endometrial cancer (2 papers); cervical cancer (1); irritable bowel syndrome (1).